PTH (parathyroid hormone)
Diseases named in the same sentence as PTH in open-access papers (continued):
Sharing a sentence is not in itself a finding about the gene and the disease.
chronic kidney disease (continued). "This study investigates the time-dependent effects of cinacalcet on serum calcium, phosphorus, and parathyroid hormone (PTH) levels in 5/6 nephrectomized (NX) rats with experimental chronic renal insufficiency." (PMID 24303131, 2013). "The mean difference in serum uric acid level between the extreme quintiles of PTH was 19 μM (0.31 mg/dl), whereas the difference among individuals with chronic kidney disease (stage 2 or higher) was 26 μM (0.43 mg/dl)." (PMID 22405053, 2012). "Low serum Ca2+ and chronic kidney disease lead to secondary hyperparathyroidism which is characterized by increased PTH mRNA levels in experimental models." (PMID 19397786, 2009). "The detection of these PTH fragments to varying degrees leads to widely differing results in the various assays used, particularly in the setting of chronic kidney disease, where PTH fragments accumulate as glomerular filtration rate (GFR) falls." (PMID 17574479, 2007). "On the other hand, HF patients are more prone to develop OP and pathological fractures because of low vitamin D level, high PTH, chronic renal failure, alteration of renin–angiotensin–aldosterone system, reduced testosterone level, and metabolic effects derived from commonly used medications." (PMID 39997503, 2025). "Diabetic kidney disease compounds the problem: even in early stages (chronic kidney disease 2–4), mineral-balance disturbances appear, which might magnify the PTH–WMH link." (PMID 41050279, 2025). "In chronic renal failure, the decrease in calcitriol production and changes in vitamin D metabolism, as well as disturbances in calcium (Ca) and phosphorus homeostasis collectively lead to the accelerated synthesis of parathyroid hormone (PTH)." (PMID 40943697, 2025). "Second-generation PTH assays measure not only the full-length, biologically active PTH 1–84 but also large C-terminal PTH fragments, which tend to accumulate in patients with chronic kidney disease." (PMID 40463748, 2025). "Thus, patients with chronic kidney disease produce higher levels of PTH to compensate for the reduction in calcium reabsorption." (PMID 39355148, 2024). "According to the CKD–MBD guidelines, i-PTH, a polypeptide hormone produced and secreted by parathyroid chief cells, plays an important role in bone metabolism, and plasma calcium and phosphorus concentrations need to be monitored in adult patients at the beginning of stage 3 CKD." (PMID 36818435, 2023). "In addition, hyperparathyroidism secondary to chronic renal failure is a condition characterized by abnormal metabolism of calcium and phosphate and inappropriate secretion of parathyroid hormone." (PMID 37448728, 2023). "Davidovits demonstrated that headache was associated with haemodialysis, the number of medications used by patients, high phosphor levels, chronic kidney disease grade, lower glomerular filtration rate, anaemia ferritin, anaemia, and a higher parathyroid hormone level." (PMID 36849915, 2023). "Besides, FGF23 suppresses vitamin D activation and decreases PTH synthesis and secretion, the primary trigger of chronic kidney disease—mineral and bone disorders (CKD-MBD)." (PMID 35806367, 2022). "Successful PTx is essential to prevent recurrent and persistent SHPT because remnant parathyroid glands (PTGs) in the neck can be stimulated and may secrete excessive parathyroid hormone (PTH) in end-stage renal disease." (PMID 36419788, 2022). "A considerable percentage of circulating PTH in chronic kidney disease (CKD) patients is oxidized." (PMID 36293083, 2022). "By comparing the healthy population, the normal parathyroid hormone group and the elevated parathyroid hormone group, there were significant differences in intestinal flora between the two groups of patients with chronic renal insufficiency and the healthy population." (PMID 36713159, 2022). "Similarly, high serum levels of PTH negatively affect serum hemoglobin levels in patients with chronic kidney disease (CKD)." (PMID 34873402, 2021).
chronic kidney disease (continued). "Rising levels of parathyroid hormone (PTH) are common in patients with chronic kidney disease (CKD) not on dialysis and are associated with an elevated risk of morbidity (including progression to dialysis) and mortality." (PMID 34170509, 2021). "Moreover, individuals with chronic kidney disease, even in early stages of renal failure, when phosphate and PTH levels were still within the normal ranges, were shown to have increased concentration of FGF23 with a concomitant decrease of serum Klotho." (PMID 34603200, 2021). "Because of the lack of consistent data on this subject, we aimed to compare both PTH assays during MIP in patients with an estimated Chronic Kidney Disease Epidemiology Collaboration (CKD-EPI) equation > 30 mL/min/1.73 m2 and to identify the predictors of IOPTH decline." (PMID 32256573, 2020). "Initial stages of both chronic kidney disease and ESRD are associated with enhanced coronary as well as aortic and mitral valvular calcification and thus, a rise in parathyroid hormone, calcium-phosphate products, and excess 1,25 hydroxyvitamin D among other metabolic abnormalities." (PMID 32850251, 2020). "In addition to chronic kidney disease (CKD)-mineral bone disorder, a high serum phosphate level and high intact parathyroid hormone (iPTH) level are known risk factors for cerebral hemorrhage in patients on HD." (PMID 31174486, 2019). "Accurate reference ranges for PTH may facilitate more reliable diagnosis and management of conditions such as primary hyperparathyroidism and end-stage renal disease." (PMID 31273631, 2019). "In addition, parathyroid hormone (PTH) was shown to stimulate a thermogenic gene program in 5/6 nephrectomized mice (a model of chronic kidney disease) that suffer from cachexia." (PMID 28677104, 2018). "Moreover, it has been shown that excess PTH in subjects with chronic renal failure plays a major role in the genesis of the glucose intolerance of uremia." (PMID 29151224, 2018). "Elevated PTH is considered a putative uremic toxin in patients with chronic kidney disease." (PMID 30214382, 2018). "Increased FGF23 levels may be one of the earliest detectable markers of chronic kidney disease, prior to changes in calcium, phosphorous, or even parathyroid hormone (PTH)." (PMID 29633705, 2018). "Severe SHPT persisted and was treated with paricalcitol 2.0 mcg per day during conservative therapy and 2.6±0.6 mcg per day during dialysis; after 40 months chronic renal disease-mineral bone disorders therapy had produced a decrease in intact parathyroid hormone to 102 pg ml−1." (PMID 26926587, 2016). "Only a few associations of vitamin D with a range of outcomes are probable according to the authors including birth weight, dental caries in children, maternal vitamin D concentrations at term, and parathyroid hormone (PTH) concentrations in patients with chronic kidney disease requiring dialysis." (PMID 27775585, 2016). "Interestingly, a significant relationship between FGF-23 and PTH was previously documented in chronic kidney disease and HF patients." (PMID 26308451, 2015). "Serum phosphorus in chronic kidney disease (CKD) patients accumulates with the decrease of glomerular filtration rate (GFR), which cause secondary elevation of parathyroid hormone (PTH) level and consequently reduces calcitriol concentration by inhibiting its secretion and promoting its metabolism." (PMID 25799184, 2015). "In addition, elevated levels of parathyroid hormone were observed in 84% of domestic cats with chronic renal failure." (PMID 26086731, 2015). "The pathophysiological downside of this regulation may occur in diseases such as chronic kidney disease, where PTH and FGF23 are chronically elevated due to decreased renal 1,25(OH)2D production and phosphate retention." (PMID 24434184, 2014). "It was shown that serum FGF-23 levels increased before PTH began to rise in chronic kidney disease." (PMID 25295189, 2014).
chronic kidney disease (continued). "However, spontaneous 25(OH)D levels > 20 ng/mL seem sufficient to control serum intact parathyroid hormone (iPTH) in chronic kidney disease (CKD) patients." (PMID 24774860, 2014). "Next, we analyzed the association of age, high blood pressure (systolic blood pressure≥140 mmHg and/or diastolic blood pressure≥90 mmHg), chronic kidney disease (eGFR<60 mL/min.1.73 m2), UA, intact PTH, and FGF23 with LV hypertrophy by multivariate logistic regression analysis." (PMID 24340056, 2013). "In rats with 5/6th nephrectomy-induced chronic renal failure, the levels of serum phosphorus and PTH observed in vehcile-treated control animals after 12 weeks of treatment were higher than those seen in animals with normal renal function treated for 13 weeks in the previous study, as expected." (PMID 21332344, 2011). "Serum intact PTH was elevated (1020 pg/ml; normal values, 12 62 pg/ml), but her serum calcium was normal (total = 9.4 mg/dl, nv 8.5–10.5; ionized = 5.0 mg/dl, nv 4.2–5.4) due to the coexistence of chronic renal failure." (PMID 20454761, 2010). "Furthermore, clinical data from patients with chronic kidney diseases should be useful in evaluating the interactions among calcitriol, PTH, and FGF23." (PMID 19838340, 2009). "We report a case of 60 year old Caucasian female with history of long standing diabetes and chronic kidney disease stage 5 who presented with a very high calcium phosphorous product, markedly elevated intact PTH levels and X-ray changes consistent with diagnosis of calciphylaxis." (PMID 18811973, 2008). "Randomized trials of vitamin D supplementation on parathyroid hormone (PTH) levels in patients with chronic kidney disease (CKD; divide by 2.5 to convert from nmol/l to ng/ml)." (PMID 39875204, 2025). "PTH levels were low across the entire study group, except in two patients with chronic kidney disease (CKD)." (PMID 40284609, 2025). "PTH was only moderately increased in the setting of chronic kidney disease (CKD) (203 μmol/L creatinine, 35 mL/min/1.73 m2 estimated glomerular filtration rate [eGFR])." (PMID 40231466, 2025). "In patients with chronic kidney disease (CKD), SGLT2 inhibitors have been associated with alterations in bone and mineral metabolism, including increased serum phosphate, fibroblast growth factor-23 (FGF-23), and parathyroid hormone (PTH) levels, along with decreased 1,25-dihydroxyvitamin D levels." (PMID 40517274, 2025). "In advanced chronic kidney disease, hyperphosphatemia, decreased extracellular calcium and decreased 1,25 (OH) Vit D3 lead to continuous stimulation of the parathyroid glands via direct and indirect mechanisms resulting in increased parathyroid hormone (PTH) production and release." (PMID 39001249, 2024). "PTH concentrations more than three times the upper range limit showed significant association with the risk of new fracture, but so did CKD patients exhibiting PTH levels in the normal range, albeit significantly lower than expected for a subject with end-stage renal disease undergoing dialysis." (PMID 38785509, 2024). "Previous research about chronic kidney disease–mineral and bone disorder (CKD-MBD) showed that hyperphosphatemia, hypercalcemia, or high PTH levels are associated with CVD events." (PMID 38922148, 2024). "The current study’s findings demonstrate a statistically significant relationship between chronic kidney disease (CKD) markers, specifically creatinine and urea, and parathyroid hormone (PTH) levels." (PMID 39484207, 2024). "One of the primary effects of 1,25(OH)2D3 and indeed most effective agonists of this hormone is to suppress PTH levels in various disease states that include chronic kidney disease (CKD) and perhaps other diseases characterized by inflammation." (PMID 37441497, 2023). "The mineral metabolism disturbances resulting from CKD and rising PTH levels are currently considered part of the definition of chronic kidney disease–mineral and bone disorder (CKD-MBD)." (PMID 37834950, 2023).
chronic kidney disease (continued). "PTH levels begin to rise beginning in stage 3 chronic kidney disease (CKD) such that SHPT is present in nearly all those with end-stage kidney disease (ESKD) at the time of dialysis initiation." (PMID 38707996, 2023). "The rise in PTH reflects both the patient's diagnosis of hyperparathyroidism and worsening chronic kidney disease (CKD)." (PMID 36408083, 2022). "The parathyroid hormone concentration ([PTH]) rises as the glomerular filtration rate (GFR) falls in patients with chronic kidney disease (CKD)." (PMID 35913960, 2022). "Secondary hyperparathyroidism (sHPT) is a common sequela of chronic kidney disease (CKD), with intact PTH (iPTH) levels typically starting to rise once the glomerular filtration rate drops below approximately 45 ml/min." (PMID 34595186, 2021). "SHPT is a chronic kidney disease- (CKD-) mineral and bone disorder and is characterized by alterations in serum calcium, phosphate, intact parathyroid hormone (iPTH), vitamin D, and FGF23; bone abnormalities; and vascular calcification." (PMID 33868402, 2021). "Chronic kidney disease‐mineral and bone disorder (CKD‐MBD) in dogs is associated with hypovitaminosis D, increased parathyroid hormone (PTH), and increased fibroblast growth factor‐23 (FGF‐23) concentrations." (PMID 33128421, 2020). "RFA has been shown to be particularly feasible for optimally treating SHPT patients with chronic kidney disease (CKD) whose PTH level is > 800 pg/mL31." (PMID 32277134, 2020). "Confirmation of the effect of 1,25(OH)2D3 on PTH levels in humans came from findings in patients with chronic kidney disease (CKD) (see later)." (PMID 30393837, 2019). "In addition to its role in the calcium and phosphor balance, PTH with increased serum levels in the patients of chronic renal insufficiency may also induce the uremic neurotoxin." (PMID 31126169, 2019). "It is quite important to control the levels of serum calcium (Ca), phosphate (P) and parathyroid hormone (PTH) properly in patients who undergo maintenance hemodialysis (HD) because of stage 5 chronic kidney disease (CKD)." (PMID 29593281, 2018). "Consistent with this, elevated FGF23 levels are associated with inflammatory markers as well as parathyroid hormone (PTH) in various disease states, including chronic kidney disease (CKD)." (PMID 29527594, 2018). "SHPT, a component of Chronic Kidney Disease-Mineral and Bone Disorder (CKD-MBD) is defined by the presence of elevated parathyroid hormone (PTH) level as well as abnormalities in mineral and bone metabolism." (PMID 30602972, 2018). "Kidney diseases are characterized by an impaired glomerular filtration rate and in the first stages of chronic kidney disease (CKD) the phosphate concentration in plasma is maintained by PTH and FGF23." (PMID 30037054, 2018). "However, some studies have demonstrated that elevated PTH levels are common even in healthy people with neither 25(OH)D deficiency nor chronic renal failure." (PMID 28115793, 2017). "Whether an association between PTH and hemoglobin also exists in patients with chronic kidney disease not on dialysis (CKD-patients) is still unclear." (PMID 25113067, 2015). "Abnormalities in the levels of calcium, phosphorus, and parathyroid hormone (PTH) in serum are typical for patients with chronic kidney disease (CKD)." (PMID 26266360, 2015). "One of the greatest therapeutic challenges in the chronic kidney disease population is the management of bone and mineral metabolic parameters in order to preserve bone integrity, minimize cardiovascular calcification, and manage serum levels of parathyroid hormone (PTH), calcium and phosphorus." (PMID 23509710, 2013). "Chronic kidney disease patients in the registry from November 2007 through November 2011 with a complete set of observations of estimated glomerular filtration rate, calcitriol, albumin, free calcium, phosphate, and parathyroid hormone were included in the study (n = 284)." (PMID 23865435, 2013).
chronic kidney disease (continued). "Current guidelines of the National Kidney Foundation for patients with chronic kidney disease recommend the measurement of calcidiol in patients with CKD stage 3 or 4 only in case of elevated parathyroid hormone levels." (PMID 23857217, 2013). "Calcimimetic agents lower serum parathyroid hormone levels in people with chronic kidney disease (CKD), but treatment effects on patient-relevant outcomes are uncertain." (PMID 23637579, 2013). "Background/Objectives: Chronic kidney disease-mineral and bone disorder (CKD-MBD) is characterized by complex interactions between parathyroid hormone (PTH), fibroblast growth factor 23 (FGF23), phosphate, calcium, and vitamin D, yet clinical decisions are often based on static individual values." (PMID 42194651, 2026). "A 46-year-old female with ADPKD-related end-stage renal disease (ESRD) was evaluated for renal transplantation and found to have an elevated parathyroid hormone (PTH) level." (PMID 42226858, 2026). "According to the Kidney Disease: Improving Global Outcomes (KDIGO) guidelines, it is primarily recommended for Chronic Kidney Disease (CKD) Stage 5D (end-stage renal disease, ESRD) to reduce PTH levels in dialysis-dependent patients with SHPT." (PMID 40170738, 2025). "Anemia worsened over time, while parathyroid hormone (PTH) levels rose, indicating progression of chronic kidney disease." (PMID 40861755, 2025). "The pathophysiology involves the accumulation of calcium in the skin, vascular space, and adipose tissue due to abnormal serum levels of calcium, phosphorus, and parathyroid hormone (PTH), particularly in patients with end-stage renal disease (ESRD)." (PMID 40557169, 2025). "Parathyroid hormone (PTH) is a surrogate marker in the clinical prediction of renal osteodystrophy and fracture in chronic kidney disease." (PMID 39974195, 2025). "This suggests a potential indirect effect of indoxyl sulfate on PTH hypo-responsiveness, which could contribute to the development of adaptive hyperparathyroidism in chronic kidney disease (CKD)." (PMID 40669844, 2025). "Parathyroid hormone (PTH) measurement is key for diagnosing parathyroid disorders, and for management of chronic kidney disease." (PMID 40937300, 2025). "Adynamic bone disorder, common in chronic kidney disease (CKD), results from reduced bone turnover, often due to medications such as calcimimetics or high-dose vitamin D analogs that induce low parathyroid hormone (PTH) levels." (PMID 40669844, 2025). "Chronic Kidney Disease–Mineral Bone Disorder (CKD-MBD) is a complex syndrome, defined by the KDIGO as a term used to collectively describe the mineral (e.g., phosphorus, calcium, parathyroid hormone (PTH)), bone (osteodystrophy), and soft-tissue calcification that develop as a complication of CKD." (PMID 41013372, 2025). "Patients with end-stage renal disease were assessed before and 28 months after KT using FGF23, PIP, and PTH serum concentrations and transthoracic echocardiography." (PMID 40115543, 2024). "Chronic kidney disease–mineral and bone disorders (CKD-MBD), marked by disturbances in mineral metabolism including phosphate, calcium and parathyroid hormone (PTH) levels, are prevalent complications among dialysis patients." (PMID 39188768, 2024). "On the other hand, a PTH measurement is essential in the diagnosis of calcium/phosphorus metabolism disorders, parathyroid dysfunction monitoring, and chronic kidney disease (CKD) patient care." (PMID 36920734, 2023). "Chronic kidney disease-related mineral and bone disorder (CKD-MBD), characterized by abnormalities in calcium, phosphate, and parathyroid hormone metabolism, with impaired bone turnover and extravascular calcification is a known complication of advanced chronic kidney disease (CKD)." (PMID 38050530, 2023).